MIR99A (microRNA 99a)
Synonyms: hsa-mir-99a; MIRN99A; mir-99a
Gene: MicroRNA gene on chromosome 21 (16,539,089 to 16,539,169, forward strand). Ensembl gene ENSG00000207638.
Gene Ontology:
Biological process: miRNA-mediated post-transcriptional gene silencing
Cellular component: RISC complex
Homologues: Orthologues: chimpanzee ptr-mir-99a (100% identical), macaque mml-mir-99a (100% identical), pig MIR99A (100% identical), rabbit MIR99A (100% identical), rat Mir99a (98% identical), zebrafish dre-mir-99-1 (81% identical), zebrafish dre-mir-99-2 (79% identical), guinea pig MIR99A (78% identical), mouse Mir99a (78% identical), tropical clawed frog xtr-mir-99 (75% identical), dog MIR99A-1 (72% identical). Paralogues in human: MIR100 (75% identical), MIR99B (62% identical), MIR125B2 (53% identical), MIR125A (51% identical), MIR10A (49% identical), MIR10B (43% identical), MIR125B1 (42% identical).
Diseases named in the same sentence as MIR99A in open-access papers:
MIR99A is named in the same sentence as 1 disease in open-access papers, as found by Europe PMC text mining. Sharing a sentence is not in itself a finding about the gene and the disease.
MIR99A shares sentences with these, for which no sentence is quoted: cancer (1 paper).